IL9 (interleukin 9)
Description:
Multifunctional cytokine secreted mainly by T-helper 2 lymphocytes and also mast cells or NKT cells that plays important roles in the immune response against parasites. Affects intestinal epithelial permeability and adaptive immunity. In addition, induces the differentiation of specific T-cell subsets such as IL-17 producing helper T-cells (TH17) and also proliferation and differentiation of mast cells. Mechanistically, exerts its biological effects through a receptor composed of IL9R subunit and a signal transducing subunit IL2RG. Receptor stimulation results in the rapid activation of JAK1 and JAK3 kinase activities leading to STAT1, STAT3 and STAT5-mediated transcriptional programs. Induction of differentiation genes seems to be mediated by STAT1 alone, while protection of cells from apoptosis depends on STAT3 and STAT5.
Synonyms: IL-9; HP40; P40
Tractability: Antibody: a drug acting on it is in phase 2 or 3 trials; its Gene Ontology location is reachable by antibodies, with high confidence; UniProt places it where antibodies can reach, with medium confidence; UniProt predicts a signal peptide or a membrane-spanning region.
Target class: Secreted protein
Gene: Protein-coding gene on chromosome 5 (135,892,246 to 135,895,841, reverse strand). Ensembl gene ENSG00000145839.
Subcellular location: Secreted
Pathways (Reactome):
Immune System: Interleukin-9 signaling
Gene Ontology:
Molecular function: cytokine activity; interleukin-9 receptor binding; cytokine receptor binding; growth factor activity
Biological process: interleukin-9-mediated signaling pathway; inflammatory response; positive regulation of cell population proliferation; positive regulation of interleukin-5 production; immune response; positive regulation of cell growth
Cellular component: extracellular region
Genetic constraint (gnomAD): Loss-of-function variants: 16 observed, 13.11 expected, observed/expected ratio (o/e) 1.22, 90% interval 0.82 to 1.78. The upper end of that interval is the gene's LOEUF score, 1.78, which puts it in group 6 of 6, group 1 being the genes least tolerant of losing a copy. Missense variants: 140 observed, 154.04 expected, observed/expected ratio (o/e) 0.91, 90% interval 0.79 to 1.05. Synonymous variants: 59 observed, 59.66 expected, observed/expected ratio (o/e) 0.99, 90% interval 0.8 to 1.23.
Homologues: Orthologues: chimpanzee IL9 (99% identical), macaque IL9 (88% identical), guinea pig IL9 (62% identical), pig IL9 (62% identical), rabbit IL9 (62% identical), rat Il9 (58% identical), dog IL9 (56% identical), mouse Il9 (56% identical), tropical clawed frog il9 (22% identical).
Diseases named in the same sentence as IL9 in open-access papers:
IL9 is named in the same sentence as 371 diseases in open-access papers, as found by Europe PMC text mining. Sharing a sentence is not in itself a finding about the gene and the disease. The quoted sentences say what the papers report.
asthma (164 papers, 2005 to 2026). "IL-9 is primarily involved in promoting mast cell activity and regulating IgE production; these are linked to the pathogenesis of asthma and protecting the body against parasitic infections." (PMID 40573262, 2025). "Th9 cells, through secretion of cytokines such as IL-9, IL-10, and IL-21, are implicated in amplifying Th2-associated lung inflammation, with IL-9 considered a particularly important mediator of asthma pathology." (PMID 41515904, 2025). "Th2 cells are pathogenic in asthma because they produce high amounts of the prototypical type 2 cytokines IL-4, IL-5, IL-9, and IL-13." (PMID 41145900, 2025). "Genetically predicted asthma was positively associated with elevated levels of IL-5 and IL-9, indicating the downstream effects of IL-5 and IL-9 on asthma." (PMID 39175819, 2024). "Th2 cells promote airway inflammation by production of a range of cytokines including IL-4, IL-5, IL-9, IL-13 and IL-25, which together are responsible for the development of hallmark features of asthma." (PMID 39598682, 2024). "Pathogenic roles for IL-9 have been identified in several allergic and autoimmune diseases, including atopic dermatitis, asthma, colitis and multiple sclerosis." (PMID 39763655, 2024). "IL-9 is associated with the development of asthma, particularly its contribution to airway inflammation and increased sensitivity." (PMID 39407835, 2024). "As a central regulator of de novo fatty acid synthesis, ACC1 expression in T cells contributes to some of the diseases that have been associated with IL-9, such as asthma, psoriasis and colitis." (PMID 39763655, 2024). "Functionally, Th2A cells have increased expression of IL-5 and IL-9 but a similar expression of IL-4 and IL-13 compared with conventional Th2 cells, aligning with the asthma-associated cluster identified transcriptionally." (PMID 37163370, 2023). "Both activated Th2 cells and ILC2s produce large amounts of the type-2 cytokines IL-4, IL-5, IL-9, and IL-13, which in turn trigger hallmark asthma symptoms." (PMID 37612281, 2023). "IL-9 has been reported to be associated with the development of allergic diseases, including asthma, and a recent Mendelian randomization analysis also suggested an association between circulating IL-9 and periodontal disease." (PMID 37959214, 2023). "Although IL-5+ and IL-13+ Tc cell levels were increased in all patient groups compared to HCs, IL-9+ Tc cell frequencies were specifically associated with uncontrolled asthma." (PMID 37612281, 2023). "Using HDM-challenged murine models of asthma, our data further indicated that IL-9 deficiency reduced proliferation of target cells (ILC2 cells, Th2 cells and mast cells) and infiltration of eosinophils." (PMID 35524325, 2022). "In the present study, we have established a murine model of asthma using wild type (WT) and IL-9-deficient (Il9−/−) mice and then investigated the distribution of mast cells, Th2 cells and ILC2 cells, following sensitization to and challenge with HDM." (PMID 35524325, 2022). "In fact, eosinophils express biologically active IL-9 that is linked to the pathogenicity of airway allergic diseases as asthma by influencing the recruitment of effectors cells." (PMID 36160152, 2022). "Previous studies have addressed the role of IL-9 in inducing changes associated with human asthma by investigating the airways of animals by blockade or genetic knock-down of IL-9 designed to induce allergic inflammation or over expression of IL-9." (PMID 35524325, 2022). "In the study of allergic asthma, it was found that IL-9 participates in the pathogenic development of asthma." (PMID 36172190, 2022). "A murine model of asthma was established using wild type (WT) and IL-9-deficient (Il9−/−) transgenic mice sensitized to house dust mite (HDM)." (PMID 35524325, 2022). "Risk factors for allergy development included IL-9 and IL-17A, cytokines which have been associated with asthma." (PMID 33722194, 2021).
asthma (continued). "Several pathophysiological pathways are associated with the development of asthma, including those that mediate the release of cytokines involved in the inflammatory process, in particular IL-4, IL-9, IL-13, and IL-17." (PMID 33577738, 2021). "One more study found that study subjects with the dominant genotype for these IL-9 polymorphisms (rs11741137, rs2069885, and rs1859430) were associated with a severe asthma exacerbation if exposed to increased dust mite levels (p = 0.02 to 0.03)." (PMID 33953642, 2021). "Several IL-9 variants (rs31563, rs1859430, rs11741137, and rs2069885) have already been published and identified as potential biomarkers for atopic dermatitis, asthma and its severity, respiratory syncytial virus (RSV) infection, and pituitary adenoma." (PMID 33953642, 2021). "Studies using IL-9-deficient mice demonstrated the redundant role of this cytokine in a similar model of asthma." (PMID 32258172, 2020). "The most precise role of IL-9 was found to be associated with human allergic inflammation, both IL-9 and IL-9R was found to be genetically linked to human asthma." (PMID 31164892, 2019). "IL-9 found to be associated with human conditions, such as allergy and asthma, as both IL-9 and IL-9R found to have genetic association with human asthma." (PMID 31164892, 2019). "Most of the initial studies on IL-9 were conducted in Th2-biased Balb/c animal models, and therefore it was suggested that IL-9 enhance Th2-associated disease pathogenesis in Leishmania infection as well as allergic inflammation in asthma." (PMID 31164892, 2019). "Similar to PU.1-deficient mice, IRF-4-deficient mice display attenuated signs of development of IL-9-dependent OVA-induced allergic inflammation in lungs in mouse model of asthma." (PMID 29867972, 2018). "The objective was to quantify the dose-response relationships between urinary PAHs metabolites and adult asthma, and analyze the potential associations between urinary PAHs metabolites and expression of plasma IL-9 and eotaxin." (PMID 29769601, 2018). "Nonetheless, the genetic association studies identified the association of IL-9 and IL-9R with human asthma, which was further validated in mouse model of allergic inflammation in asthma." (PMID 29867972, 2018). "Recent studies have shown that Th9 cells have been implicated in airway inflammation and asthma pathogenesis mainly due to the production of IL-9." (PMID 29339772, 2018). "IL-2 and IL-9 are closely interlinked in directing ILC2 biology and enhanced IL-9 expression is linked to an asthma-like phenotype in mice and humans underscoring the importance of these cytokines." (PMID 29760695, 2018). "Studies have shown that Th9 cells primarily secrete IL-9 to mediate the immune response in several diseases, such as asthma, autoimmune diseases, and parasitic infections, and IL-9 is associated with impaired Th1 immune response in patients with tuberculosis." (PMID 28484466, 2017). "IL-9 is known to play crucial role in allergic inflammation in asthma as both IL-9 and IL-9R were shown to be genetically associated with the disease." (PMID 28993609, 2017). "Th9 cells, a new type of CD4+T lymphocytes, mainly secrete interleukin (IL)-9 and IL-10, which are closely linked with asthma." (PMID 27518187, 2016). "IL-9 is a multi-effector cytokine acting on various inflammatory and tissue cells, producing various biological effects, and is closely associated with asthma." (PMID 27518187, 2016). "Polymorphisms of the IL9 gene have been linked to increased development of asthma, atopy and respiratory syncytial virus (RSV)-induced respiratory disease." (PMID 26936133, 2016). "As a great body of previous studies have revealed that IL-9 produced by Th9 cell promoted pathogenic processes in several autoimmune diseases, such as allergy and asthma." (PMID 26509179, 2015).
asthma (continued). "Th9 cells, which mainly secrete IL-9, are major contributors to the onset and progression of asthma inflammation; IL-9 is associated with mucus hypersecretion, bronchial hyperreactivity, and increased Th2 cytokine expression." (PMID 26565810, 2015). "MEDI-528 is a humanized immunoglobulin G1 monoclonal antibody that binds to IL-9, and hence reduces the activity of a variety of cell types implicated in asthma pathogenesis." (PMID 24050312, 2013). "IL-9 has previously been associated with inflammatory diseases in several studies, especially in relation to allergies and asthma." (PMID 24023645, 2013). "Interleukin 9 (IL-9) has been implicated in mast cell-related inflammatory diseases, such as asthma, where vascular endothelial growth factor (VEGF) is involved." (PMID 22413008, 2012). "For over two decades, IL-9 has been recognized as a cytokine whose elevated expression is linked to asthma and some related allergic disorders." (PMID 23071516, 2012). "Overexpression of IL-9 in murine models of asthma has been shown to cause airway inflammation with pulmonary infiltration of eosinophils and lymphocytes, airway obstruction, and mast cell hyperplasia." (PMID 21356110, 2011). "If the resultant inflammatory response is T helper-2 dominant, cytokine mediators typically associated with asthma [interleukin (IL)-4, IL-5, IL-9, IL-13] would subsequently be produced." (PMID 20064771, 2010). "In animal models of asthma the overexpression of IL-9 causes BAL eosinophilia, peribronchial accumulation of collagen and increased BAL levels of CCL5 and CTGF." (PMID 18315837, 2008). "Recent work has shown that another epithelial-derived alarmin, called TL1A, can act with IL-33 to increase IL-9 production by ILC2s, which then becomes pathogenic, suggesting that IL-9 might represent an interesting target in asthma." (PMID 41145900, 2025). "Importantly, our unbiased proteomic analyses revealed that IL-9, a type 2 cytokine associated with allergic inflammation and asthma, was the most induced protein in ILC2s costimulated with IL-33 and TL1A." (PMID 38597952, 2024). "Collectively, RNAseq Data show a distinct gene expression associated with anti-viral, immune regulation, IL-9 induction, asthma and lung injury, may make Foxo1fl/fl.CD4Cre+ mice resistant to SARS-CoV-2 infection." (PMID 37429848, 2023). "IL-9, a pleiotropic cytokine, has been implicated in the pathogenesis of many atopic diseases; including allergic rhinitis, asthma, atopic dermatitis, contact dermatitis, and food allergy; through a variety of activities on mast cells, epithelial cells and smooth muscle cells." (PMID 35524325, 2022). "Interleukin-9 (IL-9)-producing CD4+ T helper cells (Th9) have been implicated in allergy/asthma and anti-tumor immunity, yet molecular insights on their differentiation from activated T cells, driven by IL-4 and transforming growth factor-beta (TGF-β), is still lacking." (PMID 36241625, 2022). "Additionally, genome-wide expression profiles showed that young asthmatics with a IL-9 polymorphism were more likely to report a severe asthma exacerbation to HDM." (PMID 34868033, 2021). "It is encoded by the human IL-9 gene, a candidate gene for asthma." (PMID 32093397, 2020). "Although it has been suggested that IL-9 is involved in steroid-resistant asthma, the reason underlying this difference remains unclear." (PMID 31216735, 2019). "Genetic studies have revealed that the IL-9 receptor is associated with asthma susceptibility, and elevated IL-9 mRNA and IL-9 immunoreactive cells are found in lungs from asthmatics compared to patients with chronic bronchitis, sarcoidosis and healthy controls." (PMID 31191511, 2019). "Loss of Foxo1 attenuates IL-9 in Th9 cells and ameliorates allergic inflammation in asthma." (PMID 30692989, 2018).
asthma (continued). "Group II ILCs specifically, secrete the cytokines IL-5, IL-13, IL-9, amphiregulin, and low quantities of IL-4 and have been linked to several lung-associated conditions including pathogen infections (viruses and helminths), asthma, and pulmonary fibrosis." (PMID 30413212, 2018). "Consistently, administration of anti-IL-9 neutralizing antibody in murine models of asthma decreased the severity of disease associated with attenuated infiltration of eosinophils and AHR, suggesting a crucial role of IL-9 in progression of allergic inflammation in asthma." (PMID 29867972, 2018). "Both IL-9 and IL-9R polymorphism are found to be genetically associated with asthma." (PMID 29867972, 2018). "Furthermore, loss of Foxo1 suppresses IL-9 production in mouse and human Th9 and Th17 cells and substantially ameliorates allergic inflammation in asthma." (PMID 28993609, 2017). "We found significantly positive association between plasma IL-9 production and adult asthma risk." (PMID 29138487, 2017). "The most important characteristic feature of asthma is chronic airway inflammation which is associated with increased number of Th2lymphocytes and their cytokines (IL-4, IL-5, IL-9, and IL-13) while Th1 lymphocytes and their cytokines (IL-2, IFN-γ, and IL-12) are reduced." (PMID 28824424, 2017). "Furthermore, loss of Foxo1 attenuates IL-9 in mouse and human Th9 and Th17 cells, and ameliorates allergic inflammation in asthma." (PMID 28993609, 2017). "While IL-9 has been implicated as a pathogenic mediator of asthma and allergic disorders, recent studies suggest that IL-9 may enhance as well as dampen the progression of various autoimmune disorders." (PMID 24023645, 2013). "Interest in IL-9 was first triggered by genetic linkage studies and supported by the finding that expression of IL-9 and its associated receptor is higher in the airways of subjects with asthma compared with healthy controls." (PMID 24050312, 2013). "Further evidence has come from in vitro studies showing that IL-9 enhances the growth and/or activity of a variety of cell types and pro-inflammatory and pro-fibrotic mediators that are implicated in the pathogenesis of asthma." (PMID 24050312, 2013). "IL-9 induced the release of Th2-associated chemokines in cultured human airway smooth muscle cells and enhanced the stem cell factor-dependent growth of human mast cell progenitors, particularly those from children with asthma." (PMID 24050312, 2013). "This is one of the reasons why, traditionally, asthma has been associated with type 2 (T2) respiratory inflammation, characterized by elevated levels of IgE, eosinophils, and certain cytokines such as IL-4, IL-5, IL-13, and IL-9, canonically associated with allergic responses." (PMID 40650018, 2025). "In fact, administration of anti-IL-9 neutralizing antibody after allergen sensitization reduced allergic inflammation in murine model of asthma associated with attenuation in inflammatory cell infiltration, indicating the crucial role of IL-9 in development of asthma." (PMID 29867972, 2018). "Hence, we hypothesized that levels of PAHs exposure might be associated with asthma through changing the expression levels of IL-9 and eotaxin." (PMID 29769601, 2018). "In addition, anti-interleukin-9 and anti-interleukin-13 decreased symptoms associated with asthma." (PMID 26101464, 2015). "The reduced levels of IL-4 and IL-9 in the non-T2 asthma imply diminished Th2 and Tfh cell support for IgE class-switch and allergic response." (PMID 41601686, 2026). "Together, these data indicate that systemic IL-4, IL-9, and TNF-α skewing characterizes T2-high asthma overall, while non-T2 pediatric asthma is marked by elevated Th1/Th17-associated and pro-inflammatory cytokines that are largely absent in adults." (PMID 41601686, 2026). "IL-9 promotes the survival and proliferation of histamine-producing mast cells and contributes to several features of asthma, including airway hyperresponsiveness." (PMID 41145900, 2025).